PNPT1 (polyribonucleotide nucleotidyltransferase 1)
Diseases named in the same sentence as PNPT1 in open-access papers:
PNPT1 is named in the same sentence as 69 diseases in open-access papers, as found by Europe PMC text mining. Sharing a sentence is not in itself a finding about the gene and the disease. The quoted sentences say what the papers report.
melanoma (6 papers, 2013 to 2023). A malignant, usually aggressive tumor composed of atypical, neoplastic melanocytes. "Importantly, we show that this regulation is dependent on PNPT1, a human polynucleotide phosphorylase with 3’-to-5’ exoribonuclease activity, which has been implicated in the degradation of several mature miRNAs (e.g. miR-221 and miR-222) in melanoma cells." (PMID 28394930, 2017). "Human polynucleotide phosphorylase (PNPT1) selectively degrades specific miRNAs in human melanoma cells." (PMID 36834853, 2023). "Two PNPT1 transcripts estimated as about 2.6 and 4.3 kb long were originally identified in HO-1 melanoma cells, with the shorter one being more abundant than the long one." (PMID 35163574, 2022). "Previous studies on PNPT1-mediated miRNA degradation suggests that PNPT1 degrades mature miR221 and is involved in the growth and proliferation of melanoma cells." (PMID 31940341, 2020).
cerebellar ataxia (5 papers, 2011 to 2025). A neurological syndrome characterized by clumsy and uncoordinated movement of the limbs, trunk, and cranial muscles.
hearing loss (4 papers, 2018 to 2024). "Mutations in PNPT1, which encodes PNPase, cause several disorders including hearing loss and Leigh syndrome." (PMID 33633744, 2020). "Interestingly, in human, hearing loss is frequently associated with PNPT1 mutations, with or without other neurological symptoms depending on the mutations, and PNPT1 knock-out in inner ear hair cells causes hearing loss in mice." (PMID 35163574, 2022).
Aicardi-Goutières syndrome (3 papers, 2021 to 2024). "Certainly in the autoimmune vasculitis variants known as Aicardi-Goutières syndrome, where altered degradation of cytosolic DNA or RNA is caused by mutations in TREX1/SAMHD1/RNASEH2A/B/C/ADAR/IFIH1/PNPT1, the progressive immune activation leads to phenotypes of neuro-inflammation/-degeneration." (PMID 34345994, 2021).
Leigh syndrome (3 papers, 2018 to 2024). "Additionally, several recent clinical reports demonstrate that patients suffering from hereditary hearing loss, delayed myelination, axonal neuropathy, and Leigh syndrome have mutations in PNPT1, the gene encoding hPNPase." (PMID 30307990, 2018).
viral infection (3 papers, 2019 to 2023). "The components of this minimal gene signature related to IL-6 include DHX58, IFIH1, ISG15, and PNPT1, which it shares with the gene signature observed after yellow fever vaccination." (PMID 33244316, 2020).
bladder cancer (2 papers, 2023 to 2024). "An exoribonuclease polyribonucleotide nucleotidyltransferase (PNPT1), also known as polynucleotide phosphorylase (PNPase), has been reported for promoting cisplatin-induced apoptosis in bladder cancer when overexpressed was identified exclusively in P2." (PMID 38769554, 2024). "In bladder cancer (BC), miR-183-5p regulates cell apoptosis by targeting PNPT1 and BMF to inhibit the outer mitochondrial membrane permeability of BC cells." (PMID 37372440, 2023). "In bladder cancer (BC), miR-183-5p regulates BC cell apoptosis by targeting PNPT1(Polyribonucleotide nucleotidyl transferase 1) and BMF(Bcl2 modifying factor) to inhibit the outer mitochondrial membrane permeability of BC cells." (PMID 37372440, 2023).
Choreoathetosis (2 papers, 2015 to 2024). Involuntary movements characterized by both athetosis (inability to sustain muscles in a fixed position) and chorea (widespread jerky arrhythmic movements). "Recessive mutations in the PNPT1 gene, encoding PNPase, were recently linked to human mitochondrial disease in two siblings affected by encephalomyopathy, choreoathetosis, and combined OXPHOS deficiency, and in three siblings from a second family affected by non-syndromic hearing loss." (PMID 25806043, 2015).
COVID-19 (2 papers, 2022 to 2023). A disease caused by infection with severe acute respiratory syndrome coronavirus 2. "Among the transcripts related to the term “mitochondrial gene expression,” polyribonucleotide nucleotidyltransferase 1(PNPT1) showed the highest upregulation in the COVID-19 cohort, followed by MRPL24 and MRPS12." (PMID 36443881, 2022). "Of these, 6 genes were found to be shared between COVID-19 and epilepsy, including SMEK2, PNPT1, EFEMP1, CCDC85A, VRK2, and BCL11A, all located on chromosome 2." (PMID 37781245, 2023). "Further, FUMA analysis identified six overlapping genes, including SMEK2, PNPT1, EFEMP1, CCDC85A, VRK2, and BCL11A, shared between COVID-19 and epilepsy." (PMID 37781245, 2023).
Fanconi syndrome (2 papers, 2023 to 2025). "Supporting this notion, we found that PNPT1-knockout mice exhibited a Fanconi syndrome-like phenotype in terms of impaired reabsorption." (PMID 36869030, 2023). "Moreover, tubular-specific PNPT1-knockout mice display Fanconi syndrome-like phenotypes with impaired reabsorption and significant renal tubular injury." (PMID 36869030, 2023).
hepatocellular carcinoma (2 papers, 2022 to 2023). A malignant tumor that arises from hepatocytes. "Our results suggest that SP1 and NFY binding sites work as a single cis-element within the PNPT1 promoter, and that in hepatocellular cancer overexpressing PNPase, the promoter activity of PNPT1 depends on SP1 and/or NFY." (PMID 36232701, 2022).
atherosclerosis (1 paper, 2018). A disease characterized by the build-up of fatty material and calcium deposition in the arterial wall resulting in partial or complete occlusion of the arterial lumen. "Even though our finding supports a role of PNPT1 as a candidate gene in atherosclerosis, we acknowledge that PNPT1 variant is unlikely to be causal and cannot explain the linkage signal at chromosome 2 to cIMT." (PMID 30356672, 2018).
autosomal dominant Spinocerebellar Ataxia (1 paper, 2024). "As a complicated Hereditary Spastic Paraplegia, autosomal dominant Spinocerebellar Ataxia, or inherited neurometabolic disorders were suspected, a large next-generation sequencing-based gene panel testing disclosed the heterozygous pathogenic variant c.162-1G>A in intron 1 of the PNPT1 gene." (PMID 40757543, 2024).
breast carcinoma (1 paper, 2024). "It has also been reported in breast cancer that depletion of PNPT1 results in radioresistance." (PMID 38769554, 2024).
cognitive decline (1 paper, 2024). "Clinicians must be aware of the possibility of PNPT1 pathogenic variants in cases of spastic ataxia and spastic paraplegias that are associated with optic atrophy and marked cognitive decline, regardless of the established family history of neurological compromise." (PMID 40757543, 2024).
fatty liver disease (1 paper, 2024). A reversible condition wherein large vacuoles of triglyceride fat accumulate in liver cells via the process of steatosis. "Our study is the first to reveal a crucial role of PNPT1 in the pathogenesis of metabolic-associated fatty liver disease." (PMID 39218215, 2024).
Hyperglycemia (1 paper, 2023). An increased concentration of glucose in the blood. "This study further identified the reduction of renal tubular PNPT1 induced by TGFβ1, hyperglycemia or LPS as the mechanism underlying the relocation of mt-dsRNAs from mitochondria into the cytoplasm." (PMID 36869030, 2023). "Although the underlying molecular basis remains unknown, mechanistical studies indicate that PNPT1 reduction in renal tubular cells can be achieved by renal tubular cell injury factors TGFβ1, hyperglycemia and LPS." (PMID 36869030, 2023).
ischemia-reperfusion injuries (1 paper, 2023). "Analysis of tubular atrophic tissues from renal dysfunction patients and male mice with ischemia-reperfusion injuries (IRI) or unilateral ureteral obstruction (UUO) treatment shows that renal tubular PNPT1 is markedly downregulated under atrophic conditions." (PMID 36869030, 2023).
Leukoencephalopathy (1 paper, 2026). This term describes abnormality of the white matter of the cerebrum resulting from damage to the myelin sheaths of nerve cells. "Enhanced type I IFN signalling has also been observed in patients with RNASET212 and PNPT1 leukoencephalopathy." (PMID 40665566, 2026).
liver cancer (1 paper, 2022). An epithelial or non-epithelial malignant neoplasm that arises from the liver. "Consequently, the regulation of the formation of the SP1/NFY complex could be the underlying cause for the rise in the PNPT1 expression associated with a poor outcome in liver cancer patients." (PMID 36232701, 2022).
lung adenocarcinoma (1 paper, 2024). A carcinoma that arises from the lung and is characterized by the presence of malignant glandular epithelial cells. "Analysis of The Cancer Genome Atlas (TCGA) database showed that PNPase (PNPT1) gene expression was up-regulated significantly in a subset of lung adenocarcinoma (LUAD) and lung squamous cell carcinoma (LUSC) lines." (PMID 38955468, 2024).
oral cancers (1 paper, 2020). "The effect of FXR1, PNPT1, and miR301a-3p expression suggests that the miRNA-mediated p21 regulation can be targeted to reduce the growth and proliferation of oral cancers." (PMID 31940341, 2020). "The data here provides evidence that FXR1 bound with miR301a-3p is protected from PNPT1 mediated degradation in oral cancer cells." (PMID 31940341, 2020). "We provide evidence that miR301a-3p expression is rescued by downregulation of both FXR1 and exoribonuclease PNPT1 in oral cancer cells suggesting that FXR1 acts as a stabilizing factor for miR301a-3p against PNPT1." (PMID 31940341, 2020). "In this report, we describe a pathway of miRNA regulation in which FXR1 represses PNPT1-mediated degradation in oral cancer cells." (PMID 31940341, 2020). "Our data suggest that FXR1 represses PNPT1-mediated degradation of miR301a-3p in oral cancer cells." (PMID 31940341, 2020). "Conversely, our findings suggest that PNPT1 mediated degradation of miR301a in HNSCC can be protected by FXR1, leading to the repression of p21 aiding to poor prognosis of oral cancer." (PMID 31940341, 2020). "In the absence of FXR1, miR301a-3p is degraded by PNPT1, increasing p21 protein translation, and in turn, promoting cellular senescence of the oral cancer cells." (PMID 31940341, 2020). "Exoribonuclease PNPT1 degrades miR301a-3p in the absence of FXR1 in oral cancer cells, and the degradation is rescued in the FXR1 and PNPT1 co-knockdown cells." (PMID 31940341, 2020).
renal dysfunction (1 paper, 2023). "Compared to non-renal tubular injury donors, patients with various renal dysfunctions displayed a markedly reduced PNPT1 levels in injured renal tubules." (PMID 36869030, 2023).
renal fibrosis (1 paper, 2023). A final common manifestation of a wide variety of chronic kidney diseases characterized by glomerulosclerosis and tubulointerstitial fibrosis. "Masson staining of kidney tissue sections from WT and PNPT1-knockout mice also showed a significantly higher degree of renal fibrosis in PNPT1-knockout mice than in WT mice." (PMID 36869030, 2023).
rickets (1 paper, 2023). Bone softening and weakening usually caused by deficiency or impaired metabolism of vitamin D. Deficiency of calcium, magnesium, or phosphorus may also cause rickets. "Bone mineral density scanning showed that PNPT1-knockout mice had a severe bone structure deformation similar to that in rickets with a markedly lower bone mineral density compared to WT mice." (PMID 36869030, 2023).
Sepsis (1 paper, 2022). Sepsis is defined as life-threatening organ dysfunction caused by a dysregulated host response to infection. "We also found that the expression of PNPT1, which encodes a key enzyme in mitochondrial RNA metabolism, was downregulated in the sepsis group—the loss of the activity of PNPT1 results in combined respiratory chain deficiency." (PMID 36443881, 2022). "Therefore, PNPT1 downregulation in sepsis supports the failed apoptosis in sepsis samples." (PMID 36443881, 2022).
spastic ataxia (1 paper, 2024). "A diagnosis of PNPT1-related spastic ataxia was established." (PMID 40757543, 2024).
infection (10 papers, 2013 to 2025). The state of being infected such as from the introduction of a foreign agent such as serum, vaccine, antigenic substance or organism. "We turned our attention to Pnpt1, which showed the highest infection-induced change in acetylation (AcK site K250) and which was up-regulated at 6 hour p.i.." (PMID 40880474, 2025). "Knockdown of PNPT1 in HK2 cells strongly inhibited whole protein translation at 24 h post-infection, suggesting that the role of cytosolic mt-dsRNAs induced by PNPT1 reduction in HK2 cells is largely through activating PKR to shut off general protein synthesis." (PMID 36869030, 2023). "Interestingly, the levels of miR-29b-2-5p, but not of other mature microRNAs from the same precursor, are decreased upon Shigella replication at late times post-infection, through degradation of the mature microRNA by the exonuclease PNPT1." (PMID 28394930, 2017). "Moreover, knockdown of PNPT1 led to increased Shigella infection both at early and late time points, revealing its relevance in the context of infection, at least in part dependent on miR-29b-2-5p regulation." (PMID 28394930, 2017). "Moreover, we have analyzed the expression of PNPT1 during the course of infection (0.5, 3 and 6 hpi) and in sorted populations of cells with internalized Shigella (Shigella +) and bystander cells (Shigella -)." (PMID 28394930, 2017). "However, the increase of infection observed in PNPT1 knockdown cells at the early times post-infection (binding and 0.5 hpi) cannot be explained by changes in the miR-29b-2-5p expression." (PMID 28394930, 2017). "At 12 and 24 h post-infection, HK2 cells with PNPT1 knockdown displayed significantly higher levels of p-PKR and p-eIF2α compared to control HK2 cells although the total amounts of PKR and eIF2α in PNPT1-knockdown and control HK2 cells remained similar." (PMID 36869030, 2023). "Another gene PNPT1, which was documented recently to be released from mitochondria coordinately with CYCS and to possess a new pro-apoptotic role, was similarly increased in line 72 spleen samples after infection." (PMID 31252692, 2019).
cancer (7 papers, 2020 to 2024). A tumor composed of atypical neoplastic, often pleomorphic cells that invade other tissues. "PNPT1 gene maps to 2p15–2p16.1 in which alterations such as deletion and amplification are involved in human cancers, such as diffuse large B-cell lymphoma and various genetic disorders." (PMID 36232701, 2022). "In summary, our results show the relevance of SP1 and NFY in PNPT1 expression, and point to SP1/NFY and PNPase as possible targets in anti-cancer therapy." (PMID 36232701, 2022). "These upregulated target genes are enriched for the pathways involved in metabolism (e.g., SLC3A2, SLC7A5) and mitochondrial gene expression (e.g., PNPT1), consistent with previous studies, demonstrating that elevated MYC/MYCN induces metabolic reprogramming in cancer cells." (PMID 32060267, 2020).
tumor (5 papers, 2015 to 2024). "A previous study has showed PNPT1 as a tumor‐associated antigen in CD‐40‐activated leukemic cells." (PMID 33037736, 2020). "Our results suggest that in the context of tumor cell cultures, SP1 shows a more relevant role than NFY in driving PNPT1 expression." (PMID 36232701, 2022).
renal diseases (1 paper, 2023). "A significant reduction of renal tubular PNPT1 is found in different renal diseases which are associated with various degrees of renal injury." (PMID 36869030, 2023). "Although no such PNPT1 deficiency or mutation has been linked to renal diseases, our results clearly show that PNPT1 activity is required to maintain the normal function of renal tubular cells." (PMID 36869030, 2023).
PNPT1 also shares sentences with these, for which no sentence is quoted: acute pneumonia (3 papers); Ataxia (2); cystitis (2); encephalomyopathy (2); leukodystrophies (2); mitochondrial disease (2); pernicious anemia (2); Alexander disease (1); anemia (1); autoimmune vasculitis (1); axonal neuropathy (1); CODAS syndrome (1); dentatorubral-pallidoluysian atrophy (1); depression (1); epilepsy (1); Friedreich ataxia (1); gestational diabetes (1); glucosuria (1); hereditary spastic paraplegia (1); hypothyroidism (1); inflammation (1); lactic acidosis (1); Lethal congenital contracture syndrome type 3 (1); lung squamous cell carcinoma (1); MELAS syndrome (1); mitochondrial cytopathy (1); mitochondrial DNA depletion syndrome 5 (1); mitochondrial encephalomyopathy (1); myoclonic epilepsy (1); optic atrophy (1).
A further 8 diseases each share a sentence with PNPT1 in 1 paper.